FOXM1 (forkhead box M1)
Diseases named in the same sentence as FOXM1 in open-access papers (continued):
Sharing a sentence is not in itself a finding about the gene and the disease.
glioma (continued). "In this section, we will discuss the importance of FOXM1 in glioma progression, alongside mentioning its upstream and downstream regulators." (PMID 37821870, 2023). "The MELK/FOXM1 axis has received more attention in recent years due to its significance in high-grade gliomas, and newer investigations have uncovered other upstream regulators involved in chromatin remodeling, such as SAT1 in the regulation of MELK and EZH2." (PMID 37821870, 2023). "FOXM1 and FOXOs have been recognized as crucial transcription factors in tumor cells, including glioma cells." (PMID 37821870, 2023). "Due to this, using a dual inhibitor of histone deacetylases (HDAC) and PI3K, such as CUDC-907, can suppress the expression and transcriptional activity of FOXM1 in high-grade gliomas, leading to radiosensitization." (PMID 37821870, 2023). "In gliomas, FOXM1 promotes tumorigenesis by direct interaction with β-catenin and acts as a cofactor for β-catenin stabilization." (PMID 37667311, 2023). "Few studies have reported the relationship between ferroptosis and FOXM1, and our study revealed that FOXM1 inhibits ferroptosis by increasing FA synthesis, reducing the accumulation of ROS and lipid peroxidation products in glioma cells." (PMID 37620304, 2023). "Meanwhile, Forkhead box M1 (FoxM1) mediates temozolomide resistance in glioma cells by regulating the expression of RFC5." (PMID 37251536, 2023). "High expression of FOXM1 in glioma cells enhances tumorigenicity, invasiveness and angiogenesis in GBM animal models." (PMID 35978012, 2022). "Relevant studies have shown that MYBL2 is a key downstream factor of the Akt/FoxM1 signaling pathway in promoting human glioma progression and can be used as a new candidate gene for glioma molecular targeted therapy and a biomarker for radiotherapy." (PMID 36133745, 2022). "FOXM1, a key mediator of the Wnt/β-catenin pathway, is overexpressed in many human cancers, including glioma." (PMID 35978012, 2022). "FOXM1 has been associated with cell migration, invasion, stemness, mesenchymal (MES) transition, and resistance to radiotherapy in gliomas." (PMID 35409080, 2022). "The researchers found that Akt/FoxM1 (Forkhead box M1) signaling pathway-mediated up-regulation of MYBL2 (MYB-related protein B2) fosters progression of human glioma." (PMID 35935338, 2022). "The knockdown of MTDH would inhibit the expression of MYBL2 through decreasing the expression of FoxM1 and further reduce glioma cell proliferation and cell migration and invasion." (PMID 36133745, 2022). "For example, in glioma, the self-renewal and tumorigenicity of CSCs were regulated by dysregulated Wnt–FoxM1/β-catenin signaling pathway." (PMID 35338348, 2022). "FOXM1 is involved in tumorigenesis and transformation of normal astrocytes, reflects the histological malignancy of glioma, and is proposed to be a surrogate marker for OS." (PMID 35785200, 2022). "Preclinical studies of glioma cells showed that FOXM1 directly interacts with β-catenin and promotes nuclear translocation." (PMID 36151566, 2022). "Expression of FOXM1B, the predominant isoform of FOXM1 expressed in human gliomas, strongly correlated with poor prognosis and was regulated by GLI1." (PMID 36010600, 2022). "Recent studies have demonstrated that low expression of MYBL2 induces cell cycle arrest, apoptosis, and epithelial–mesenchymal transition (EMT) in glioma cells, and it is positively regulated by FoxM1, a member of the forkhead box transcription factor family." (PMID 36133745, 2022). "FOXM1/β-catenin interactions can also regulate the stemness and tumorigenicity of glioma stem cells." (PMID 35978012, 2022). "Taken together with inhibition studies aiming the Akt/FOXM1 signaling, these results propose that transcription factor MYBL2 functions as a key downstream component of the Akt/FOXM1 axis, promoting the progression of gliomas." (PMID 35409080, 2022).
glioma (continued). "MYBL2 has also been proved to be associated with poor prognosis of cancer by pan-cancer analysis, and some literatures have shown that MYBL2 can be upregulated by activation of Akt/FoxM1 to promote the development of glioma." (PMID 36133745, 2022). "The key mitotic genes essential for proliferation of glioma stem cells were also regulated by FOXM1 phosphorylation in an MELK-dependent manner." (PMID 36353126, 2022). "A recent study showed that low level of miR-320a promoted glioma proliferation through FOXM1 expression." (PMID 35444548, 2022). "For example, heatshock factor 1 (HSF1) can bind to the FOXM1 promoter and upregulate its expression when glioma cells are subjected to lethal heat shock stress." (PMID 34205406, 2021). "We showed that glioma patients with high FOXM1 expression had a worse prognosis than patients with low FOXM1 expression in the TCGA database." (PMID 34740322, 2021). "It has been reported that DKK1 is a direct target of Wnt signaling in various cells and that FOXM1 binds directly to β-catenin and promotes its nuclear localization and β-catenin-dependent transcriptional activity in glioma cells." (PMID 34117362, 2021). "First, although the expression level of circCCDC66 was detected in a small sample size of glioma samples, a larger sample size should be used to further verify the correlation between the expression of circCCDC66, miR-320a and FOXM1 and clinical parameters." (PMID 34252882, 2021). "Aberrantly expressed ASPM regulated by transcriptional factor FoxM1 triggers the malignant progression of gliomas." (PMID 34987580, 2021). "During tumorigenesis, FoxM1 expression increases as cells differentiate from neural progenitor cells to pretumorigenic progenitors, and then to glioma stem-like cells." (PMID 33691791, 2021). "To validate the TCGA results, we checked the mRNA and protein expression levels of FOXM1 in normal brain tissues and human glioma samples." (PMID 34740322, 2021). "Relative to normal human astrocytes, the expression of ANXA2R in those cells was elevated only in patient-derived WG4 glioma cells; while FOXM1 expression was significantly elevated in 4 out of 5 cell lines." (PMID 34131149, 2021). "For example, the removal of m6A promotes the binding of FOXM1 pre-mRNA to the RNA-binding protein HuR, and improves its stability, resulting in enhanced expression of FOXM1 protein, which in turn promotes the proliferation of the glioma cells." (PMID 33926508, 2021). "In this project, we found that circCCDC66 was over-expressed and that the expression of FOXM1 was increased by sponge miR-320a, which promoted the progression of glioma cells." (PMID 34252882, 2021). "We demonstrate that both migration and invasion of glioma cells were significantly reduced in FOXM1-depleted cells with downregulated ANXA2R expression." (PMID 34131149, 2021). "The expression of circCCDC66 is increased in gliomas, which promotes tumor development and metastasis by regulating FOXM1 expression through miR-320a." (PMID 34252882, 2021). "On the other hand, the transcription factor, FOXM1, which is known as human proto-oncogene, can maintain the activity of glioma stem cells (GSCs) and can promote the activity of β-catenin to regulate Wnt target gene expression in GSCs43." (PMID 34535705, 2021). "Among these targets, we selected FOXM1, which has been reported to play a vital role in the occurrence and development of glioma as potential components of the circPIK3C2A-miR-877-5p ceRNA network." (PMID 35004326, 2021). "We demonstrate that both migration (as tested in a scratch assay) and invasion of glioma cells (tested in a Matrigel assay) were significantly reduced in FOXM1-depleted cells with downregulated ANXA2R expression." (PMID 34131149, 2021). "Relationship analysis indicated that NOX4 and FOXM1 expression are correlated with each other in glioma." (PMID 34740322, 2021).
glioma (continued). "To confirm the function of FOXM1 in the development of glioma, we investigated the expression of FOXM1 in normal brain and glioma specimens with different grades." (PMID 34740322, 2021). "FoxM1 directly regulates the expression of MMP-2 at the transcriptional level to promote glioma progression." (PMID 32429421, 2020). "Similar to previous studies, we also found that FoxM1 is highly expressed in gliomas and its high expression predicts the poor prognosis of glioma patients." (PMID 32667745, 2020). "Referring to previous studies, FOXM1 binds to β-catenin and facilitates its nuclear translocation in tumor cells, such as in leukemia, osteosarcoma, glioma, and lung cancer." (PMID 32513952, 2020). "We examined the mRNA and protein expression levels of FoxM1 in different glioma cell lines and found that FoxM1 was highly expressed in U87‐MG cells and less expressed in Hs683 cells." (PMID 32667745, 2020). "After treatment with a dual HDAC and PI3K inhibitor in high grade pediatric glioma, the expression and transcriptional activity of FOXM1 decreased, which is consistent with our finding that FOXM1 expression was altered." (PMID 32210076, 2020). "Collectively, our results demonstrated for the first time that aberrant ASPM expression mediated by transcriptional regulation of FoxM1 promotes the malignant properties of glioma cells." (PMID 32667745, 2020). "For example, in pancreatic cancer and glioma, FOXM1 was found to stimulate invasion and angiogenesis via regulation of MMPs." (PMID 32961773, 2020). "MYBL2 (MYB Proto‐Oncogene Like 2) is a member of the MYB family of TF genes, is a key downstream factor of AKT/FOXM1 signalling to promote progression of human glioma." (PMID 32696617, 2020). "We found that BRCA1, CHD1 and FoxM1 mRNA expression was significantly positively correlated with ASPM mRNA expression in glioma tissues, and the highest correlation coefficient was found between FoxM1 and ASPM expression." (PMID 32667745, 2020). "In glioma, FOXM1 interacts with β-catenin to enhance its nuclear translocation and ability to promote self-renewal and tumorigenesis." (PMID 32035486, 2020). "In summary, the present study is the first to reveal that ASPM promoted glioma cell proliferation, migration and invasion and tumour growth, which is mediated by the transcriptional activation of FoxM1." (PMID 32667745, 2020). "Studies have also reported that FOXM1 promoted glioma resistance to TMZ chemotherapy via regulating DNA damage repair gene Rad51 and replication factor C5." (PMID 31796105, 2019). "Mechanistically, bortezomib down-regulated the FOXM1–Survivin axis, which was also found to be up-regulated in glioma patients and was related to poor prognosis." (PMID 31796105, 2019). "The up-regulation of the FOXM1–Survivin axis in clinical samples can, at least partially, confirm our results and indicated the potentiality of bortezomib in glioma chemotherapy." (PMID 31796105, 2019). "Expression levels of FOXM1 and Survivin were positively correlated with each other and both related to poor prognosis in glioma patients." (PMID 31796105, 2019). "In our present study, another oncogene, the anti-apoptotic factor Survivin, was found to be regulated by FOXM1 in glioma cells." (PMID 31796105, 2019). "In regard to glioma, FOXM1, as an oncogenic transcription factor, also plays important roles in glioma progression and maintenance of GSC characteristics." (PMID 31796105, 2019). "Transcription factor FoxM1 positively regulates UBE2C expression to protect glioma cells from autophagic death." (PMID 30914455, 2019). "A knock down of FOXM1 decreased nuclear translocation of FOXM1 and reduced protein concentration of beta catenin in the nucleus of colon cancer and glioma, respectively." (PMID 31541075, 2019). "In our TMZ-insensitive U251 and U87 glioma cell lines, the expression levels of FOXM1 and Survivin were markedly up-regulated." (PMID 31796105, 2019).
glioma (continued). "In several clinical studies, a link between aberrant expression levels of the transcription factor FOXM1 and poor prognosis for many cancers including breast, liver, lung prostate, melanoma and gliomas have been described." (PMID 31541075, 2019). "Accordingly, an increased FoxM1 expression in glioma cells enhanced their tumorigenicity, invasiveness, and angiogenesis." (PMID 29462960, 2018). "To investigate the association of FoxM1 and ADAM17 with the MES phenotype, we first analyzed the expression levels of FoxM1, ADAM17 and mesenchymal markers in glioma specimens from The Cancer Genome Atlas (TCGA)." (PMID 29700308, 2018). "There are reports showing the biological interaction between FoxM1 and β-catenin in glioma, medulloblastoma and colon cancer." (PMID 29423068, 2018). "FOXM1 was shown to stimulate angiogenesis in several cancers, including pancreatic cancer, gastric cancer and glioma, through induction of vascular endothelial growth factor (VEGF), matrix metalloproteinase-2 (MMP-2) and MMP-9." (PMID 30486864, 2018). "Ours and others studies have provided compelling evidence that FoxM1 played critical roles in glioma progression." (PMID 29700308, 2018). "To examine the roles of FoxM1 in MES transition of glioma cells, we first performed transfection using sh-FoxM1 and sh-EGFP plasmids in U251MG and U87MG cells." (PMID 29700308, 2018). "A very comprehensive review pointed out that the expression level of FoxM1 protein in human glioma tissue is directly correlated with tumor grade and inversely correlated with patient survival." (PMID 29462960, 2018). "Forkhead box M1 (FOXM1), a member of the Fox family, functions as an oncogene in multiple cancers such as glioma and lung cancer." (PMID 30021604, 2018). "Both MYBL2 and FoxM1 levels were significantly higher in glioma than in normal tissues, similar to the IHC results." (PMID 28784180, 2017). "We knocked down of MYBL2 and FoxM1 by siRNA in glioma cells and found that down-regulation of FoxM1 significant reduced MYBL2 protein expression; while down regulation of MYBL2 did a little change of FoxM1 expression." (PMID 28784180, 2017). "In our previous gene expression profile analysis (GSE54936 and GSE53464), FoxM1 was downregulated in human glioma and ovarian cancer cells after treatment with the Hh-Gli signaling pathway inhibitor GANT61." (PMID 28148279, 2017). "In the present study, two transcription factors MYBL2 and FoxM1 emerge as synergistic initiators and master regulators of glioma progress and transformation." (PMID 28784180, 2017). "Since our results above indicated the correlation of FoxM1 and MYBL2 in glioma progression, we further study the mechanism of MYBL2 and FoxM1 expression in glioma." (PMID 28784180, 2017). "To investigate the functions of MYBL2 and FoxM1 expression in glioma, we up and down regulated both genes in low and high-grade glioma cells." (PMID 28784180, 2017). "In this study, we also found that UBE2C expression was strongly correlated with FoxM1 expression in gliomas." (PMID 28767320, 2017). "TAGLN2 knockdown significantly decreased the level of Fork head box M1 (FoxM1), an oncogenic transcription factor essential for cancer progression in various types of cancers including gliomas." (PMID 29110682, 2017). "Taken together, these findings suggest that FoxM1 transcriptionally regulates UBE2C expression by directly binding to the UBE2C promoter in glioma cells." (PMID 28767320, 2017). "In our previous studies of the oncogenic roles of this molecule, we found that FoxM1 up-regulation increased and FoxM1 down-regulation inhibited angiogenesis in glioma cells." (PMID 28767320, 2017). "Forkhead box M1 (FoxM1) promotes glioma tumorigenicity through the WNT pathway partly by inducing EMT." (PMID 28556516, 2017). "The aim of the present study was to investigate the clinical significance of the correlation between MYBL2 and FoxM1 in glioma and the possible mechanism of FoxM1and MYBL2 expression." (PMID 28784180, 2017).
glioma (continued). "We evaluated the effects of MYBL2 and FoxM1 on overall survival of the glioma patients using Kaplan-Meier analysis and log-rank test." (PMID 28784180, 2017). "To identify the molecular mechanism for the effects of MYBL2 and FoxM1 in glioma progress, we investigated the role of MYBL2 and FoxM1 in cell cycle progression and EMT." (PMID 28784180, 2017). "Directly connected with β-catenin activity is the role of Forkhead box protein M1 (FoxM1), whose abnormal expression has been often found in glioma." (PMID 29261132, 2017). "In summary, our results suggest that both MYBL2 and FoxM1 over-expression are associated with poor prognosis and EMT in glioma." (PMID 28784180, 2017). "The present study furthered our understanding of the mechanism by which FoxM1 regulates glioma oncogenesis in several ways." (PMID 28767320, 2017). "Our results showed that MYBL2 and FoxM1 were both upregulated in human glioma and influenced tumor progression." (PMID 28784180, 2017). "To test further the specificity of IGFBP2, we also analyzed MYC, FOXM1, and E2F2, which have been associated with malignant progression of IDH-mutant glioma." (PMID 27852048, 2017). "Meanwhile, MYBL2 closely related to the FoxM1 expression in 79 glioma tissues (r = 0.742, p < 0.05) and LGG (r = 0.83) and HGG (r = 0.74) cohorts of TCGA." (PMID 28784180, 2017). "FOXM1 also promotes β-catenin nuclear localization and controls Wnt target-gene expression during glioma tumorigenesis." (PMID 27259253, 2016). "At first, we investigated FOXM1 activity because FOXM1 was identified as an important substrate of MELK in glioma stem cells and its activity was attenuated by OTS167 in acute myeloid leukemia cells." (PMID 26871945, 2016). "Knowledges about beta-catenin regulation in glioma are recently increasing with R132H IDH1 mutation, FoxM1, TRIM33, HOXA13 as examples of positive or negative regulators." (PMID 27613837, 2016). "FOXM1 is a master transcription factor that regulates mitotic progression of different types of cancer cells and forms a protein complex with MELK in glioma stem-like cells, leading to phosphorylation and activation of FOXM1 in a MELK kinase-dependent manner." (PMID 26973435, 2016). "FoxM1 expression in glioma patients has been documented in the previous reports, but the number of specimens examined was rather small or only FoxM1 mRNA expression was evaluated in some cases." (PMID 26444992, 2015). "High expression levels of FoxM1 are correlated with glioma malignancy and poor patient survival, and most GBM patients express high levels of FoxM1." (PMID 26444992, 2015). "While Huang and co-workers found that heat shock factor 1 (HSF1) regulates FOXM1 in glioma with changes in cell cycle proteins, including CDC20, our results provides the first direct evidence that FOXM1 maintains TICs via regulation the expression of CDC20." (PMID 25938542, 2015). "FoxM1 also directly interacts with β-catenin during glioma tumorigenesis to induce nuclear localization of β-catenin, a clear indication of canonical Wnt signaling activation." (PMID 25714027, 2015). "The oncogenic transcription factor FOXM1 was also downregulated in PHGDH shRNA-silenced glioma cells." (PMID 25574168, 2014). "FoxM1 contributes to glioma progression by enhancing VEGF gene transcription and tumor angiogenesis." (PMID 25522167, 2014). "Our findings provide both clinical and mechanistic evidences that FoxM1 contributes to glioma development by directly up-regulating Anxa1 expression." (PMID 23991102, 2013). "To determine the FoxM1 and Anxa1 expression levels in glioma cells lines, we examined the FoxM1 and Anxa1 expression in Hs683, SW1088, LN-229, and U-87MG cell lines by RT-qPCR and Western blot." (PMID 23991102, 2013). "In conclusion, we found that FoxM1 directly regulated Anxa1 expression to promote glioma cells proliferation, migration, and angiogenesis." (PMID 23991102, 2013).